GFAP (glial fibrillary acidic protein)
Diseases named in the same sentence as GFAP in open-access papers (continued):
Sharing a sentence is not in itself a finding about the gene and the disease.
schizophrenia (55 papers, 2009 to 2026). A major psychotic disorder characterized by abnormalities in the perception or expression of reality. "A study with post-mortem tissue of patients with schizophrenia found an association between increased GFAP (glial fibrillary acidic protein, an astrocyte marker) protein and mRNA with neuroinflammation." (PMID 35903343, 2022). "Postmortem cortical expression and protein levels of major astrocyte associated genes such as glial fibrillary acidic protein (GFAP) are perturbed in schizophrenia." (PMID 29312938, 2017). "Decreased GFAP was found in association with schizophrenia models." (PMID 40747269, 2025). "Moreover, multiple injections of the NMDA receptor antagonist that causes schizophrenia-like symptoms has led to increase in the level of GFAP in the hippocampus of rats and in the medial prefrontal cortex of mice." (PMID 32116664, 2019). "GFAP is also known to have a significant association with schizophrenia." (PMID 23840971, 2013). "We found that GFAP mRNA levels were increased in high-inflammation schizophrenia (F4,138 = 5.08, p = .001) compared with all low-inflammation subgroups and in high-inflammation bipolar disorder cases compared with low-inflammation controls (all p adj." (PMID 41567988, 2026). "Several of these proteins such as GDI-1, GFAP, and MBP have been implicated in pathology of schizophrenia and ASD via neuronal-glial interactions." (PMID 40779003, 2025). "Abnormal expression of GFAP in the prefrontal cortex can lead to psychotic illnesses such as schizophrenia and bipolar disorder." (PMID 39763976, 2024). "Changes in expression of the GFAP (glial fibrillary acidic protein) gene, which is involved in the pathogenesis of schizophrenia, were observed." (PMID 37376644, 2023). "Some animal models of schizophrenia also presented increased GFAP positive astrocytes in the frontal cortex and hippocampus." (PMID 35903343, 2022). "The study compared levels of GFAP expression between subjects with schizophrenia (n = 15), BD (n = 15), MDD (n = 15), and HC (n = 15)." (PMID 36358439, 2022). "There was, however, a significant increase in gene expression of the astrocyte marker, GFAP, in the midbrain of schizophrenia cases relative to controls (F = 11.034, df = 1,53, p = 0.002)." (PMID 31168068, 2021). "GFAP mRNA was also increased in the schizophrenia/high immune subgroup compared with the schizophrenia/low immune and control subgroups (p < 0.05)." (PMID 31168068, 2021). "CD55 mRNA was not significantly correlated with any complement transcripts in any group, except for a trend toward a positive correlation with GFAP mRNA in schizophrenia (r = 0.36, p = 0.065)." (PMID 33133060, 2020). "In summary, we report increases in lactate in the DLPFC in schizophrenia, as well as abnormal lactate levels in the frontal cortex of mutant GFAP DISC1 mice and frontal cortical neurons from a schizophrenia patient." (PMID 30911039, 2019). "NMDA receptors, related with all the groups of schizophrenia symptoms, associated also with astrocytes, since NMDA antagonist increased the number of GFAP-positive astrocytes in the prefrontal cortex." (PMID 32116664, 2019). "We also report abnormalities in lactate levels in an animal model of schizophrenia, the GFAP DISC1 mouse, and frontal cortical neurons differentiated from iPSCs of a patient with the DISC1 mutation." (PMID 30911039, 2019). "The morphology of astrocytes depends on the measure of the inflammatory response in patients with schizophrenia, so the differences in morphology can partially explain the different data about the levels of GFAP." (PMID 32116664, 2019). "The levels of the astrocyte markers (GFAP, S100B) were increased unevenly in patients with schizophrenia." (PMID 32116664, 2019). "Of those 42 studies, 33 studies evaluated potential differences in astrocytes in schizophrenia by measuring GFAP expression or immunoreactive distribution." (PMID 27271499, 2016).
schizophrenia (continued). "Here, we describe for the first time, an association of schizophrenia-related behavior in Disc1 mutant mice with increased LCN2 and GFAP+ glial cells in the SVZ." (PMID 23272119, 2012). "Since FAS and TNFR1 mRNAs were highly expressed in astrocytes in schizophrenia by snRNA-seq, we measured a marker of reactive astrocytes, GFAP mRNA, to determine whether these changes could be part of a generalized astrocyte response to inflammation." (PMID 41567988, 2026). "In this sense, although we did not observe overt changes in number and morphology of astrocytes by mAb102, we did find reduced GFAP+astrocytes and therefore the potential contribution of astrocytic Plxnb2 to schizophrenia and stress disorders is worth pursuing more carefully in the future." (PMID 36325348, 2022). "We also measured transcript levels of the reactive astrocyte marker GFAP since cortical astrogliosis may exist in a subset of people with schizophrenia and reactive astrocytes reciprocally influence microglia polarization states." (PMID 35844224, 2022). "GFAP expression is different in patients with schizophrenia." (PMID 32116664, 2019). "The glial theory of schizophrenia based on the proven inflammatory response and elevated levels of the characteristic markers of active glia—S100B and glial fibrillary acidic protein (GFAP)." (PMID 32116664, 2019). "Out of the 33 studies evaluating GFAP expression, 21 did not detect any schizophrenia-associated changes, 6 studies reported a decrease in GFAP expression, whereas 6 studies reported increased expression." (PMID 27271499, 2016). "Moreover, four out of six studies examining the cingulate cortex, subgenual cingulate cortex or anterior cingulate cortex found significant changes in GFAP in schizophrenia." (PMID 27271499, 2016). "In particular, increased GFAP in schizophrenia/psychotic symptoms could be closely related to increased neuroinflammatory markers, as well as to increased IL-1beta and IL-6 serum levels." (PMID 25889039, 2015). "Interestingly, decreased expression of GFAP has been reported in other neurodevelopmental disorders, such as Schizophrenia and bipolar disorder." (PMID 24410870, 2014). "Besides, the differential expression of peroxiredoxin 6 (PRDX6) and glial fibrillary acidic protein (GFAP) were confirmed by western blot in schizophrenia prefrontal cortex." (PMID 19405953, 2009). "The increased expression of FAS and TNFR1 in astrocytes, along with increased GFAP mRNA expression and positive correlations between TNFRs and GFAP mRNAs in high-inflammation schizophrenia, suggests that reactive astrocytes could be the main source of FAS/TNFR1 in the inflamed midbrain." (PMID 41567988, 2026). "However, animal models of schizophrenia showed an increase in the level of GFAP." (PMID 32116664, 2019). "The psychotic symptoms, severity of schizophrenia symptoms, memory ability, cognitive function, serum BDNF, S100B, and GFAP levels, and incidence of adverse reactions between the two groups were compared." (PMID 41312344, 2025). "The results of this study showed that the combination of risperidone and MECT can better improve the levels of GFAP and BDNF in patients with schizophrenia." (PMID 41244550, 2025). "We also find increased reactive astrocytes (GFAP) and microglia (IBA1) mRNAs in schizophrenia midbrain, and these cells are proposed mediators of the neuroinflammatory state in schizophrenia." (PMID 40335479, 2025). "Reactive astrocyte marker GFAP mRNA (log2FC = 0.14, FDR = 0.0016) was elevated in schizophrenia and Autism groups compared to control." (PMID 35844224, 2022). "It has previously been demonstrated that patients with schizophrenia have lower serum BDNF, MBP, and GFAP levels, but higher serum IL-6 and S100B." (PMID 34025476, 2021). "Age of onset negatively correlated with CD14, IL6R, IL1R1, SERPINA3, pan-GFAP and VIM mRNAs in schizophrenia and CD14, IL1B, SERPINA3, pan-GFAP and VIM mRNAs in bipolar disorder." (PMID 34911938, 2021).
schizophrenia (continued). "For instance, the changes we observe in the GFAP DISC mice are likely driven by the well characterized mitochondrial defects found in DISC mutants, while the changes in schizophrenia are more subtle and likely secondary to a lifetime of synaptic dysfunction." (PMID 30911039, 2019). "There were 5 intermediate filament proteins with disturbed abundance in schizophrenia: desmin (DES), vimentin (VIM), glial fibrillary acidic protein (GFAP), and neurofilament medium and light chains (NEFM and NEFL)." (PMID 26909022, 2016). "Last, we investigated the mRNA expression levels of MAPK14, GFAP and the inflammation markers, IL1B and IL6 in postmortem brain tissues from schizophrenia patients." (PMID 27801899, 2016). "Indeed, we previously found increased GFAP mRNA and protein in those patients with schizophrenia who also had elevated cytokines and a positive correlation between KATI/II mRNAs and both GFAP and cytokine mRNAs in the present study." (PMID 30940904, 2020). "A moderately strong, significant, positive correlation was found between an astrocyte maker (GFAP) and KAT I mRNAs in both healthy controls (ρ = 0.57, n = 33, p = 0.001, FDR p = 0.004) and in patients with schizophrenia (ρ = 0.45, n = 36, p < 0.01, FDR p = 0.02)." (PMID 30940904, 2020). "Interestingly, we detected increased expression of GFAP, an astrocyte marker, decreased expression of MAP2, a neuronal marker, and elevated ratio of GFAP/MAP2, in postmortem brains of patients with schizophrenia." (PMID 27801899, 2016). "Nevertheless, despite more studies pointing to a decrease in GFAP expression in the cingulate cortex in schizophrenia, not all studies show decreases despite evaluating the same brain region and marker." (PMID 27271499, 2016). "Furthermore, we detected elevated expression of GFAP, a gliogenic (astrocyte) marker, in postmortem brains from schizophrenia patients without the 22q11.2 deletion, whereas inflammation markers (IL1B and IL6) remained unchanged." (PMID 27801899, 2016). "However, the RIN (pH) and GFAP expression levels in the postmortem brain samples were not significantly correlated to each other: P=0.706 (0.987), 0.585 (0.919) and 0.120 (0.682) for control, schizophrenia and total brains, respectively." (PMID 27801899, 2016). "However, the decreased GFAP mRNA in schizophrenia compared to controls overall could be due to the greater elevation of GFAP mRNA in high inflammation controls in our study, which aligns with previous studies of GFAP expression showing no change or even decreases in schizophrenia overall." (PMID 35844224, 2022). "We assessed previously published GFAP mRNA data in this cohort and found that ICAM1 and GFAP mRNA transcripts correlated in DLPFC from controls (r = 0.40, p = 0.04) but not from people with schizophrenia (r = 0.26, p = 0.16)." (PMID 30214039, 2020). "The patients with schizophrenia showed a large increase in chondroitin sulfate proteoglycan (CSPG) - positive glial cells in the deep amygdala and entorhinal cortex and the density of GFAP - positive cells was not changed at some studies." (PMID 32116664, 2019).
injury (53 papers, 2010 to 2025). Damage inflicted on the body as the direct or indirect result of an external force, with or without disruption of structural continuity. "We strategically chose to collect blood at 24 h post-match, aligning with the known peak of GFAP levels after mild traumatic brain injury and SRC, a top-performing brain-specific diagnostic candidate in these contexts." (PMID 39562417, 2025). "GFAP has been well studied in adult and paediatric traumatic brain injury and has demonstrated association with short-term outcomes, but long-term outcome studies are needed." (PMID 41383571, 2025). "This capability makes GFAP a valuable tool for distinguishing TBIs from other causes of death and understanding the mechanisms underlying fatal head trauma." (PMID 39796043, 2024). "A recent study by Hauk and colleagues showed that intravitreal injection of toll-like receptor 2 agonist Pam3Cys (caused lens injury) can induce glial activation and upregulations of GFAP and CNTF, which significantly stimulated retinal ganglion cell axon regeneration into the injured optic nerve." (PMID 20169166, 2010). "Several molecules have been proposed as biomarkers for injury severity, response to treatment, and predictors of outcomes after head trauma, including glial acidic fibrillary protein (GFAP), neuron-specific enolase (NSE), and S100B." (PMID 39467990, 2024). "For instance, blood levels of GFAP are used as a clinical test to evaluate mild traumatic brain injury, as they are correlated with clinical severity." (PMID 37628733, 2023). "In the conditions of brain trauma, seizure and different neurodegenerative disorders, elevation of GFAP expression is observed." (PMID 37373117, 2023). "The strength of this study is that we will simultaneously measure GFAP, which is a plasma biomarker for brain injury, and the BSID-III test which is an actual measurement for neurodevelopment." (PMID 35395776, 2022). "Nevertheless, neonates with brain injury presented more frequently with GFAP levels above the lowest detection limit (0.056 ng/ml) and this trend was significantly different during all 3 days." (PMID 34278985, 2022). "Astrogliosis is characterized by the upregulation of GFAP and is observed in aging and neurodegenerative conditions, such as brain trauma, cerebral hemorrhage, and Alzheimer’s disease." (PMID 35437315, 2022). "Correlation with lesion volume is seen in other neurological disorders as well; in a recent study of 197 patients with traumatic brain injury, serum measurements of GFAP, NFL, tau and UCHL1 correlated with lesion volume on MRI." (PMID 35765081, 2022). "Brain injury measured by GFAP release in plasma has been reported before for inhaled gasoline vapors in Sprague Dawley rats." (PMID 34204780, 2021). "Of the six mTBI players (Players A–F) with markedly elevated plasma GFAP or NFL, three had clinical features suggestive of a more significant brain injury, including loss of consciousness, ataxia and high number of symptoms/long duration on return to play." (PMID 33543129, 2020). "Reactive astrocyte-like cells marked by glial fibrillary acidic protein (GFAP) are a widespread endogenous stem cellular potential source following brain injury." (PMID 31191223, 2019). "Glial fibrillary acidic protein (Gfap), a marker of astrogliosis, is up-regulated after CNS trauma and is used as a universal index of retinal injury." (PMID 24767545, 2014). "Recently, other reports have confirmed that serum GFAP is a specific marker of brain damage after head trauma." (PMID 21702960, 2011). "We report that blood levels of UCH-L1 and GFAP are an indicator of the severity of brain damage after severe head trauma and are correlated with prognosis after trauma." (PMID 21702960, 2011). "GFAP is increasingly recognised as a marker of neurodegenerative disorders as well as traumatic brain injury and is upregulated during gliosis in response to chemical, biological insults as well as brain trauma." (PMID 39696767, 2025).
injury (continued). "The aim of this study was to investigate the diagnostic accuracy of early prehospital S100B and GFAP measurements to rule out intracranial lesions in adult patients with mild traumatic brain injury." (PMID 34078435, 2021). "Because astrocyte activation is induced by brain injury, GFAP levels were also measured." (PMID 32415357, 2020). "GFAP is concentrated in the cytoskeleton of astrocytes and is upregulated following brain injury corresponding to astrocytic activation, making it an ideal candidate marker for brain injury patients." (PMID 33543129, 2020). "Although rmTBI did not induce a significant increase in astrocytosis compared to that of the sham group, the mean value of GFAP labeling was increased in the cortex and white matter after brain injury and a minimal decrease was observed after tDCS in this study." (PMID 28770112, 2017). "The expression of GFAP is also related to the rehabilitation process following brain injury." (PMID 27597962, 2016). "For example, treatment with synaptamide in traumatic brain injury or sciatic nerve chronic constriction injury decreased astrogliosis and immunoreactivity and reduced the levels of inflammatory biomarkers such as glial fibrillary acidic protein (GFAP), S100β, and IL-6." (PMID 38338779, 2024). "When obtained within 6 h of injury UCHL1 in combination with GFAP was very sensitive for a positive head CT, and was thought to provide the objective evidence clinicians desire when trying to reduce the use of CT scans in patients with mild traumatic brain injury." (PMID 27468268, 2016). "Therefore, the specificity of GFAP and NfL for brain trauma, especially in young adults where neurodegenerative conditions that could complicate interpretation are uncommon, emphasises their suitability for integration into the framework of head impact management in collision sport." (PMID 39562417, 2025). "In patients with craniocerebral trauma, serum levels of MMP-9, S100-β,and GFAP were found to be significantly altered." (PMID 39801405, 2025). "For example, proteomic data from only 4‐Plex assay (NfL, GFAP, tau protein, and ubiquitin c‐terminal hydrolase L1; UCH‐L1) better classified people with traumatic brain injury when compared to only single proteomic measure." (PMID 38234075, 2024). "Several studies have reported that GFAP (indicative of astrocyte activation) and CD11b expression are increased in the PAG following nerve injury." (PMID 25986444, 2015). "Unlike traditional biomarkers such as GFAP and NFL, which reflect glial and axonal injury, respectively, neurogranin highlights the synaptic dimension of brain trauma, which is highly relevant for cognitive outcomes and risk of later neurodegeneration." (PMID 40981206, 2025). "GFAP has consistently demonstrated its reliability as an indicator of brain injury severity, with elevated levels observed in patients with severe TBI, making it a potential tool for assessing the extent of brain trauma." (PMID 39796043, 2024). "In response to this stimulus, activated glia prompt the development of an ongoing neuroinflammatory state that supports the processes of neuronal degeneration, resulting in a substantial upsurge of GFAP and IBA-1, which are considered trustworthy hallmarks of a brain injury." (PMID 37834102, 2023). "Observed changes in GFAP and NSE concentration supported the assumption that S100B is released from muscles acting as a myokine rather than from the central nervous system indicating traumatic brain injury." (PMID 37063956, 2023). "The temporal profiles for serum UCHL1 and GFAP are mostly in line with the limited literature on SRC and mild traumatic brain injury, with studies to date indicating UCHL1 increases are only seen acutely (i.e. within hours) and GFAP primarily within the first 24 h of injury." (PMID 33422120, 2021). "In hypoxia-ischemia-induced brain injury, Beclin-1 has been observed to co-localize with neurons but not GFAP-positive cells." (PMID 34684832, 2021).